GJE1 (gap junction protein epsilon 1)
Description:
Mediates calcium-independent ATP release, suggesting activity as a hemichannel. Does not form functional gap junctions.
Synonyms: Cx23
Tractability: Antibody: UniProt places it where antibodies can reach, with high confidence; UniProt predicts a signal peptide or a membrane-spanning region; its Gene Ontology location is reachable by antibodies, with medium confidence.
Gene: Protein-coding gene on chromosome 6 (142,132,925 to 142,135,358, forward strand). Ensembl gene ENSG00000203733.
Subcellular location: Cell membrane
Gene Ontology:
Molecular function: gap junction channel activity
Biological process: cell-cell signaling; cell communication; transmembrane transport
Cellular component: connexin complex; plasma membrane
Homologues: Orthologues: chimpanzee GJE1 (98% identical), rabbit GJE1 (87% identical), dog GJE1 (86% identical), guinea pig GJE1 (86% identical), rat Gje1 (83% identical), mouse Gje1 (82% identical), pig GJE1 (78% identical), zebrafish gje1a (73% identical), tropical clawed frog gje1 (72% identical). Paralogues in human: GJB1 (30% identical), GJA10 (29% identical), GJA9 (29% identical), GJB2 (28% identical), GJA4 (27% identical), GJC1 (27% identical), GJA3 (27% identical), GJB6 (27% identical), GJA1 (26% identical), GJD2 (26% identical), GJA5 (26% identical), GJA8 (26% identical), and 8 more.
Diseases named in the same sentence as GJE1 in open-access papers:
GJE1 is named in the same sentence as 3 diseases in open-access papers, as found by Europe PMC text mining. Sharing a sentence is not in itself a finding about the gene and the disease. The quoted sentences say what the papers report.
cataract (1 paper, 2020). Partial or complete opacity of the crystalline lens of one or both eyes that decreases visual acuity and eventually results in blindness. "Additionally, Hsf4, Tdrd7, gap junction protein epsilon 1 (Gje1), beaded filament structural protein 2 (Bfsp2), and lens intrinsic membrane protein 2 (Lim2) which are also significantly reduced in the SCR lens (<0.5-fold) were linked to human or animal cataracts (Supplement 1)." (PMID 33204712, 2020).
myeloma (1 paper, 2022). "Polymorphisms in genes involved in nervous system function, NFATC1, NFATC4, and EDN1 were associated with CIPN in 646 myeloma patients treated with bortezomib, as were TCF4, DYNC1I1, and GJE1 in 139 myeloma patients treated with bortezmib." (PMID 35360655, 2022).
GJE1 also shares sentences with these, for which no sentence is quoted: hepatocellular carcinoma (1 paper).